CD4 (CD4 molecule)
Diseases named in the same sentence as CD4 in open-access papers (continued):
Sharing a sentence is not in itself a finding about the gene and the disease.
syphilis (continued). "IHC was more commonly positive in samples coming from patients with secondary syphilis (PR = 1.441) or second-tertiary syphilis (PR = 1.286), with anti-HIV non-reagent serology (PR = 1.444) or in immunosuppression by HIV with CD4 less than 200 cells/mm3 and VL > 1.000 copies/mL (PR = 1.133)." (PMID 36906465, 2023). "The hazard ratio for cognitive decline was not influenced by randomization status, syphilis stage, serum RPR titer, HIV status, antiretroviral use or peripheral blood CD4+ T cell concentration in PLWH, cognitive performance before treatment, BDI or WRAT-3 scores." (PMID 34255767, 2021). "The differences of gender, age, syphilis stage, and antiretroviral therapy (ART) duration between neurosyphilis group and non-neurosyphilis group were not statistically significant, so did the CD4 cell counts." (PMID 26559304, 2015). "A diagnostic examination found the following results 5 × 103 copies/mL HIV viral load; 11/μL CD4 cell count; CRF01_AE HIV sub-type; positive anti-HBs; 6.42 × 105 copies/mLHCMV-DNA; Chest X-ray detected bilateral pneumonia; floaters eyes; and negative results for herpes, HCV, and syphilis." (PMID 20230617, 2010).
prostate carcinoma (147 papers, 2001 to 2026). A carcinoma that arises from epithelial cells of the prostate gland. "In BRCA-deficient breast cancer and prostate cancer, CD4+ and CD8+ T cells exhibit a higher degree of infiltration into tumor tissues compared with the stroma." (PMID 40830526, 2025). "Our MR analysis showed that genetically‐predicted increased expression of ZNRD1 in CD4 + T cells was associated with increased risk of prostate cancer (OR = 1.06, p = 1.4 × 10−3), and the MR‐DEG test suggested the ZNRD1 effect as likely causal." (PMID 41216857, 2025). "It has been suggested that the association between LOY and disease risk depends on what type of leukocyte is affected with Y loss, with prostate cancer patients showing higher levels of LOY in CD4 + T lymphocytes." (PMID 38443832, 2024). "In monocytes-macrophages, CD4 on monocyte was found to be negatively correlated with prostate cancer risk through IVW testing (OR = 0.9975, 95%CI:0.9958–0.9992, p = 0.0047)." (PMID 38566827, 2024). "Further analysis showed that co-culture of CD4+ T cells HH and Molt-3 with prostate cancer cells including C4-2 and CWR22Rv1 cells caused higher chemo-resistance to docetaxel-induced cell death in the prostate cancer cells." (PMID 36836690, 2023). "High tumor mutation burden in HJURP and other genes in prostate cancer is associated with greater activation of memory CD4+ T cells." (PMID 35783358, 2022). "We further identify that expression of C7 significantly correlates with expression of CD4 and has the potential to alter clinical outcome in human prostate cancer, where low levels of C7 associate with poorer prognosis." (PMID 31740786, 2020). "ESR1 binding in regions associated with MS were highly enriched for Th1 CD4+ DNase I hypersensitivity peaks (7.41-fold, p < 0.0002) and those in regions associated with prostate cancer for LNCaP DNase I hypersensitivity peaks (9.39-fold, p < 0.0002)." (PMID 24171864, 2013). "Earlier studies have shown that tumour CD4+ T-lymphocyte infiltration was associated with poor outcome, independent of grade or stage, in patients with a variety of cancer including renal and prostate cancer." (PMID 18797461, 2008). "Increased CD4+ T-lymphocyte infiltration within the tumour was stage independent and associated with poor outcome in patients with prostate cancer." (PMID 15266325, 2004). "Why the presence of an increase in CD4+ T-lymphocyte infiltrate would be associated with poor cancer specific survival in patients with prostate cancer is unclear since it would seem logical that an increased T-lymphocyte infiltrate would help control and even destroy tumour cells." (PMID 15266325, 2004). "Furthermore, it has been shown that the type of leukocyte affected with LOY might be relevant for disease risks, with LOY in specifically CD4 + T lymphocytes being associated with increased risk for prostate cancer." (PMID 38443832, 2024). "CD4+T cell infiltration take part in the development and spread of prostate cancer, and neutrophils are linked to poor prognosis.Therefore, we proposed that the expression level of CD47 might affect TME through immune cell infiltration, thus regulating tumor progression." (PMID 37719086, 2023). "However, prostate cancer TIL populations are mainly composed of CD4+FOXP3+CD25+ Treg cells and M2-type tumor-associated macrophage (TAM) cells, which contribute to the production of inhibitory cytokines and the maintenance of self-tolerance to suppress the immune response." (PMID 35892678, 2022). "The TCE subtype, enriched with both CD8+ and CD4+ T cells, suggests that a robust anti-tumor immune response can translate to a favorable prognosis in prostate cancer." (PMID 41534468, 2026). "Prostate cancer-specific CD4 epitopes were selected based on the criteria of either promiscuously presented or presented by multiple class II alleles." (PMID 40520577, 2025). "Like other studies, we observed a higher density of CD8+ and CD4+ cells in higher GG prostate cancer." (PMID 39602457, 2024).
prostate carcinoma (continued). "While higher densities of CD8+ T cells are typically associated with a favourable prognosis in other tumor types, higher densities of both CD8+ and CD4+ cells have been shown to be poor prognostic factors in prostate cancer." (PMID 39602457, 2024). "In investigating the interplay between T cells and prostate cancer, we uncovered another intriguing result: CD45RA on CD39+ resting CD4 regulatory T cells is also positively correlated with prostate cancer development." (PMID 38566827, 2024). "Specifically patients with Alzheimer’s disease had more LOY in NK cells, while patients with prostate cancer displayed higher levels of LOY in granulocytes as well as CD4 + T lymphocytes." (PMID 38443832, 2024). "Men with Alzheimer’s disease develop LOY in NK cells whereas men with prostate cancer were more likely to develop LOY in CD4 + T cells and granulocytes." (PMID 38287344, 2024). "In prostate cancer, B cells, CD4 T cells, CD8 T cells, mast cells, and pDCs are upregulated, and cDCs, endothelial cells, monocytes, and plasma cells are downregulated." (PMID 39120585, 2024). "In treating prostate cancer, iodine‐125 (I‐125) therapy increases the percentage of CD4+ T cells and the ratio of CD4/CD8." (PMID 38801402, 2024). "Lactate modulates CD4+ T-cell polarization and induces an immunosuppressive tumor environment, which sustains the progression of prostate carcinoma via the Toll-like receptor 8 signaling pathway." (PMID 39830505, 2024). "Immune infiltration analysis showed that EXO1 promoted infiltration of activated CD4+positive T cells in multiple tumor types including prostate cancer." (PMID 38279172, 2024). "It has been shown that there is an increase in CD4+ T cells in the prostate tissue samples of prostate cancer patients in comparison to those from control." (PMID 36836690, 2023). "It has been reported that following chemotherapy treatment with Docetaxel, a currently approved therapy for multiple cancers including metastatic prostate cancer, the numbers of CD4+ T cells in prostate cancer patients were higher in the tumor area." (PMID 36836690, 2023). "It was found that CD4+ T cells were able to enhance prostate cancer cell migration and invasion abilities through downregulation of AR in the prostate cancer cells." (PMID 36836690, 2023). "CCL5 was identified as a responsible cytokine secreted by CD4+ T cells for this high chemoresistance of prostate cancer cells." (PMID 36836690, 2023). "The downregulation of AR expression in the prostate cancer cells resulted in recruiting more CD4+ T cells, providing a feedback loop for this interaction between the prostate cancer cells and CD4+ T cells enforcing invasiveness of the prostate cancer." (PMID 36836690, 2023). "The fraction of CD4+ T cells within the lymphocyte population of prostate cancer patients was moderately lower than in healthy controls throughout the whole follow-up but interindividual variation was high." (PMID 35804830, 2022). "The expression level of CD39 on CD4+ effector T cells was significantly higher after the 36-month follow-up of prostate cancer patients." (PMID 35804830, 2022). "In a series of experiments performed on primary CD4+ T cells stimulated with anti-CD3/anti-CD28, we demonstrated that factors (conditioned media) secreted from aged mice CD4+ T cells promote prostate cancer cell viability, migration, and invasion." (PMID 36358603, 2022). "Our laboratory has previously reported that, contrary to popular contention, prostate cancer cells and primary prostate tumors express detectable and functional HLA class II molecules capable of stimulating CD4+ T cells." (PMID 36499557, 2022). "The inhibition of EZH2 upregulates the induction of IFN-stimulated genes in prostate cancer and promotes a marked increase in CD4+ and CD8+ T cells in the TME, reversing the anti-PD-1 therapy resistance of B6-HiMYC PCa transgenic tissue transplant model." (PMID 35892678, 2022).
prostate carcinoma (continued). "We showed that in prostate cancer patients before therapy both the adaptive immune system (altered CD4+ Teff cells and increased fraction of Tregs with suppressive phenotype) and the innate immune system (decreased NK cell fraction) were altered." (PMID 35804830, 2022). "Mechanistic studies showed that the immunodominant PSMA459 epitope becomes cysteinylated under normal physiologic conditions, and this cysteinylated form of PSMA459 inhibits the CD4+ T cell recognition of prostate cancer cells." (PMID 36499557, 2022). "On the other hand, a promising strategy based on TCR isolation for neoepitope-specific TCR cloning and engineering of autologous CD8+ and CD4+ T-cells is being implemented in clinical trials that include patients with prostate cancer (NCT03970382)." (PMID 35327339, 2022). "In one mouse prostate cancer model, supplementation of CD4+ Tregs reduced inflammatory cytokine production in the prostate and led to fewer prostate cancers, while CD4+ Treg depletion had the opposite effect." (PMID 35104804, 2022). "In this study, we show for the first time that GILT insertion into prostate cancer cells directly enhances the HLA class II-restricted presentation of cysteinylated peptides and results in increased CD4+ T cell activation by prostate cancer cells." (PMID 36499557, 2022). "In that study, histological staining of cryopreserved tissues showed that CD4+ T cells were the predominant cell population in prostate carcinomas." (PMID 35754788, 2022). "Lactate regulates CD4+ T cell polarization and induces immunosuppression to promote prostate cancer progression through the TLR8/miR21 axis." (PMID 35223996, 2022). "Here, for the first time, we show that the insertion of a lysosomal thiol reductase (GILT) into prostate cancer cells directly enhances HLA class II antigen processing and results in increased CD4+ T cell activation by prostate cancer cells." (PMID 36499557, 2022). "The proportion of M0 macrophages and activated memory CD4+ T cells was higher, while neutrophils and monocytes were lower in prostate cancer tissues." (PMID 33816234, 2021). "We found that the infiltration of CD8+ T cells, CD4+ T cells, and NK cells significantly decreased during the remission and relapse of prostate cancer." (PMID 34771735, 2021). "DNA analyses of sorted cells showed that men diagnosed with Alzheimer’s disease was primarily affected with LOY in NK cells whereas prostate cancer patients more frequently displayed LOY in CD4 + T cells and granulocytes." (PMID 33837451, 2021). "High expression of CTD-3184A7.4 indicated significantly lower level of infiltrated memory resting CD4+ T cell in prostate cancer (P = 8.3E-10)." (PMID 33665192, 2021). "Radiotherapy was reported to cause a global reduction in circulating lymphocyte subsets in patients treated for stage I–II prostate cancer or to induce an increase in CD4+ Treg in the peripheral blood of patients with diverse solid cancers." (PMID 34090509, 2021). "Conversely, in prostate cancer, a carbon ion-treated patient experienced a decrease in tumor cells and rise in CD4+ cells and CD4+/CD8+ ratio during the RT and until 1 month after treatment." (PMID 31878191, 2019). "Based on the expression level of UBASH3B, we found six types of tumor-infiltrating immune cells in prostate cancer tissues, including B cells, CD4+ T cells, CD8+ T cells, macrophages, neutrophil, and dendritic cells." (PMID 32010618, 2019). "A number of studies have reported that the infiltration with CD4- or CD8-positive lymphocytes is increased in prostate cancer compared to benign prostate tissue." (PMID 31549213, 2019). "The same profile of activation of the adaptive immune response was seen in the prostate cancer patients: predominantly, CD4 T-cell responses were seen with CD8+ responses being variable, while no MUC1-reactive antibodies were induced." (PMID 29784646, 2018).
prostate carcinoma (continued). "Other studies also indicated that increased infiltration of CD4+ T cells and CD8+ T cells within the tumor was associated with a poor outcome in prostate cancer patients." (PMID 28216616, 2017). "In a transgenic adenocarcinoma mouse prostate (TRAMP) model of prostate cancer, CD4+CD25+FoxP3+ Tregs were found to be dispensable for induction of tumor-specific tolerance." (PMID 28292326, 2017). "In support of the importance of Tregs in prostate cancer, Tregs that were defined as CD4+CD25high cells with in vitro immunosuppressive function were found to be increased in prostate cancer tissues compared with non-cancerous prostate tissues." (PMID 28292326, 2017). "In another trial evaluating ipilimumab in a variety of malignancies (colon, non-Hodgkin’s lymphoma, or prostate cancer), this treatment was found to induce a long-term decrease in CD4+ Tregs (CD4+CD25+CD62L+)." (PMID 23653893, 2013). "In a Phase I trial in prostate cancer patients, treatment with ipilimumab was found to increase Treg frequency [as measured by circulating CD4+Foxp3+ T cells]." (PMID 23653893, 2013). "To confirm that CD4 T cells play a pivotal role in directing female immune responses against prostate cancer, we performed experiments to identify T cell responses against specific epitopes of antigens expressed by TRAMP-C2." (PMID 22493742, 2012). "The relationship between tumour CD4+ T-lymphocytic infiltration and cancer-specific survival is the opposite of that previously reported for both renal and prostate cancer." (PMID 15700032, 2005). "When those patients with localised or locally advanced prostate cancer (n=57) were examined in univariate analysis, only CD4+ T-lymphocyte count achieved statistical significance (HR 2.88, 95% CI 1.15–7.22, P=0.024)." (PMID 15266325, 2004). "Additionally, higher ALDH1A2 expression was positively correlated with the infiltration of all measured immune cells, including B cells, CD8+ T cells, CD4+ T cells, macrophages, neutrophils, and dendritic cells, in prostate cancer." (PMID 39781359, 2025). "In the present study, we used this technology to design a prostate cancer vaccine candidate (TENDU) containing long synthetic peptides harboring prostate cancer-derived epitopes (CD4 and CD8) from PAP, PSMA (preclinical and clinical study), and NY-ESO1 (preclinical study)." (PMID 40520577, 2025). "In this study, we showed that CIR was capable of increasing the intratumoral infiltration of CD4+ T lymphocytes and macrophages in prostate cancer‐bearing mice, whether compared with the unirradiated control or PhIR." (PMID 38379323, 2024). "While we observed this effect may be driven by IL-6 blockade, previous studies in prostate cancer observed elevated numbers of IFN-γ–producing CD4+ T cells upon administration of CTLA-4–blocking Abs." (PMID 36881480, 2023). "In addition to that, we found selective enrichment in the prostate cancer epithelium of T CD4+ cells with sparse infiltration of T CD8+ and B cells." (PMID 36811045, 2023). "Recently, Mao et al16 evaluated peripheral blood lymphocyte subtypes and clinical outcomes of 135 prostate cancer patients and reported that an absolute CD4 T lymphocyte count of less than 255/μL is an unfavorable prognostic factor for prostate cancer survival." (PMID 37877827, 2023). "We consider that the increase in the pathological stage and prostate-specific antigen value and the decrease in the number of CD4+ T lymphocyte subtypes may be prognostic markers in prostate cancer patients." (PMID 37877827, 2023). "Finally, it was also shown that activation of STAT3 in the prostate cancer cells while co-culturing with CD4+ cell lines HH and Molt-3 mediated the chemoresistance of prostate cancer cells in response to docetaxel." (PMID 36836690, 2023).